PDGFRA (platelet derived growth factor receptor alpha)
Diseases named in the same sentence as PDGFRA in open-access papers (continued):
Sharing a sentence is not in itself a finding about the gene and the disease.
glioma (continued). "PDGFRA expression was detected in 29.6% of gliomas, and more frequently expressed in 45–60% of malignant astrocytic tumours." (PMID 19707201, 2009). "PDGFA and PDGFRA expression was found in 81.2% (130 out of 160) and 29.6% (48 out of 160) of gliomas, respectively." (PMID 19707201, 2009). "PDGFRA gene amplification analysis revealed PDGFRA amplification in 21.1% (12 out of 57) of gliomas, a frequency similar to that described in previous studies." (PMID 19707201, 2009). "A previous study showed PDGFRA expression in approximately 50% of gliomas and a correlation with poor prognosis in low-grade gliomas." (PMID 19707201, 2009). "PDGFRA copy number changes (ratio >2) were observed in 52.6% (30 out of 57) of glioma patients: 18 displayed ratios <5 and were considered representative of aneuploidy/aneusomy and 12 (21.1%) harboured ratios ⩾5 and were considered amplified." (PMID 19707201, 2009). "As in low-grade glioma cells, high-grade glioma cells analyzed in this study maintained the expression profiles for PDGFRα, A2B5, O4 and CD44." (PMID 18398462, 2008). "Our data show that nearly all low-grade glioma cells from the analyzed cases concomitantly express multiple cell surface markers for glial progenitor cells, such as PDGFRα, A2B5, O4, and CD44." (PMID 18398462, 2008). "PDGFRA signaling actively remodels the glioma microenvironment, contributing to vascular abnormalities (e.g., via the PDGFRA-Endocan-MYC axis), metabolic reprogramming that impairs T cell function, and immune cell polarization, all of which restrict anti-tumor immunity." (PMID 41847712, 2026). "Human IDH mutant gliomas exhibit hypermethylation at the cohesin and CCCTC motifs, resulting in reduced CTCF protein binding, loss of insulation between TADs, and abnormal receptor tyrosine kinase gene PDGFRA activation." (PMID 40901634, 2025). "PDGFRA amplification has been shown to be a promising therapeutic target in pediatric gliomas." (PMID 40880425, 2025). "Recent studies have highlighted the oncogenic role of PDGFRA signaling in glioma." (PMID 41036308, 2025). "Notably, the majority of radiation-induced pediatric gliomas demonstrate histologically high-grade features and H3/IDH-wild-type status with PDGFRA alterations and CDKN2A/B loss, exhibiting molecular profiles similar to pHGG RTK1 or RTK2." (PMID 40853542, 2025). "Thirty-four adult patients with PDGFRA-enriched recurrent high-grade gliomas were enrolled." (PMID 40709015, 2025). "Thus, the rat glioma 101.8 strain is quite relevant as a useful translational model for preclinical evaluation of targeted anti-tumor drugs aimed at reducing PDGFRa expression." (PMID 41009560, 2025). "H3.3K27M thalamic gliomas often exhibit FGFR1 gain-of-function mutations rather than PDGFRA alterations." (PMID 40986124, 2025). "Overall, PDGFRa is one of the targets for precision glioma therapy." (PMID 41009560, 2025). "The more appealing targets for H3.3-G34 mutant gliomas are represented by PDGFRA, BRAF, and IDH1." (PMID 39202398, 2024). "On the other hand, TAMs signal the glioma cells through the PDGFB to PDGF receptor alpha (PDGFRα) axis, which could trigger downstream phosphatidylinositol 3 kinase (PI3K) and mitogen-activated protein kinase (MAPK) pathways." (PMID 38515213, 2024). "Our cases suggest that adult LFS patients also develop pediatric-type high-grade gliomas, and that PDGFRA amplification may have a high affinity for this type of glioma." (PMID 38605367, 2024). "A preclinical study demonstrated nilotinib may be effective for the management of a platelet-derived growth factor receptor alpha (PDGFRα)-dependent group of pediatric gliomas." (PMID 38686055, 2024). "The amplification of PDGFRA is also found more frequently in H3.3-altered gliomas." (PMID 39126064, 2024).
glioma (continued). "PDGFRA somatic alterations in the extracellular domain are restricted to some cancer types, such as gliomas, and their contribution to tumor development remains unclear." (PMID 38532028, 2024). "Genetic aberrations associated with worse prognoses, such as PDGFRA amplification, CDKN2A or CDKN2B deletion, and CDK4 amplification, may lead to further glioma subdivision." (PMID 38672625, 2024). "PDGFRA expression is required for the cell proliferation of glioma." (PMID 36043552, 2023). "The downstream signaling of PDGFRA increases cell survival and proliferation, and overexpression in gliomas may be a key tumorigenic step." (PMID 37509641, 2023). "However, our results provided some doubt about the prognostic and therapeutic roles of PDGFRA in glioma." (PMID 36043552, 2023). "PDGFRA amplification is correlated with the unfavorable outcomes of glioma." (PMID 36043552, 2023). "In addition, previous studies have revealed cell subtypes that are associated with glioma progression, and EGFR, NF1, and PDGFRA/IDH1 are markers for the classical, mesenchymal, and proneural types, respectively." (PMID 37371484, 2023). "Furthermore, radiation increases the risk of de novo glioma tumors with CDKN2A deletions and PDGFRA gains/amplifications." (PMID 37932833, 2023). "Moreover, PDGFRA is co‐expressed with EGFR and EGFR amplification requires PDGFRA signaling to promote the development of glioma." (PMID 36043552, 2023). "In addition, circCDK14 has also been shown to promote epithelial-mesenchymal transition in glioma cells by regulating PDGFRA expression." (PMID 37332354, 2023). "We compared the KPP model to models harboring the constitutively active PDGFRAD842V mutation, as this mutation and another similarly constitutively active PDGFRA mutation (PDGFRAV544ins) have been utilized in recently published models of H3K27M and H3.3G34R gliomas." (PMID 37011011, 2023). "The subgroup with frequent PDGFRA amplification reveals nearly the same spectrum of molecular alterations when compared with radiation-induced high-grade gliomas, which is an important finding for further understanding the mechanisms by which these secondary tumors arise." (PMID 36941392, 2023). "Furthermore, immature oligodendrocyte markers, such as the chondroitin sulphate proteoglycan NG2 and platelet-derived growth factor receptor alpha (PDGFR-α), lack specificity and have been unsuccessful in discerning between glioma types." (PMID 37274223, 2023). "Moreover, treating IDH mutant glioma spheres with a demethylating agent restored the function of an insulator and downregulated PDGFRA expression." (PMID 35382567, 2022). "Amplification of this region may lead to poorer outcomes as PDGFRA is a putative oncogene in glioma and FIP1L1 is constitutively expressed in oligodendrocyte precursor cells." (PMID 35852875, 2022). "However, in pediatric high-grade glioma, PDGFRA gene amplification is distinct from that observed in adult GBM36." (PMID 35075231, 2022). "Notably, another recent study reported the use of everolimus to improve the CNS penetration of dasatinib in PDGFRA-driven high-grade gliomas in children." (PMID 34551970, 2022). "In glioma, circCDK14 can inhibit ferroptosis and promotes its progression via regulating PDGFRA." (PMID 36266731, 2022). "Interestingly, our results were in contrast to published observations of increased PDGFRA expression in IDH‐mutant gliomas and glioma cell lines." (PMID 34767259, 2022). "Previous studies showed a higher rate of PDGFRA alterations in gliomas of CC involvement." (PMID 34636967, 2022). "Moreover, we also found that circCDK14 reduced glioma cells' sensitivity to Fp by regulating PDGFRA expression." (PMID 35002529, 2022). "This study corroborates a previous one showing the immunohistochemical expression of both NG2 and PDGFRα in various glioma types including pilocytic astrocytoma, GBM and other diffuse gliomas classified at this time as “oligodendroglioma “and “fibrillary astrocytoma”." (PMID 35563061, 2022).
glioma (continued). "Similarly, GOLM1 promotes PDGFA/PDGFRα-mediated migration and invasion of glioma through the activation of PI3K/AKT/mTOR cascade, which, in turn, induces the activation of GSK3β and the increased expression of ZEB1 and Snail." (PMID 35805075, 2022). "Aberrant PDGFRA signaling in gliomas leads to activation of the Ras-Raf-MEK-ERK pathway." (PMID 35109850, 2022). "Imatinib can induce PDGFRA phosphorylation and exert a growth inhibitory effect on glioma cells." (PMID 36685223, 2022). "Moreover, our data indicates that circCDK14 modulates glioma activity through PDGFRA regulation via miR-3938." (PMID 35002529, 2022). "Although epigenomic reprogramming in IDH1-mutant glioma also results in aberrant PDGFRA expression through the dysfunction of methylation-sensitive insulator, whether or not this is the mechanism of IDH-mutant glioma genesis remains to be investigated." (PMID 35203456, 2022). "The purpose of this study was to screen lead compounds and candidate drugs with potential inhibitors against platelet-derived growth factor receptor α (PDGFRA) from the drug library (ZINC database) in order to improve the prognosis of patients with high-grade glioma (HGG)." (PMID 36685223, 2022). "Integration of PDGFRA-WT produced both high- and low-grade gliomas with extended latencies." (PMID 35978801, 2022). "Interestingly, expression of PDGFRA, a major growth factor receptor in glioma cells, was significantly reduced in GBM, whereas PDGFRB was increased." (PMID 34470658, 2021). "PDGFRα is a cell surface tyrosine kinase receptor widely expressed by many fibroblast populations including activated CAFs, neural progenitors and pericyte cells, but also many tumor types, including glioma, prostate, and ovarian cancer." (PMID 33585217, 2020). "Furthermore, amplification peaks of oncogenes (PIK3C2B, PDGFRA, EGFR, CDK4), and deletion peaks of tumor suppressor genes (TUSC1, CDKN2A, CDKN2B, PTEN, FAS, BNIP3) were detected in the gliomas with a high risk score." (PMID 32023222, 2020). "Moreover, PDGFRA and ZEB1 cooperate to induce mesenchymal transition in adult glioma, further stressing the link between PDGFRA and mesenchymal transition." (PMID 32117746, 2020). "Although detailed mechanisms underlying these effects are yet to be elucidated, these findings imply that aberrant expression of GAG synthases, such as CHSY1, could provide a molecular basis for targeting PDGFRA pathway in glioma." (PMID 32019907, 2020). "Since different trophoblast subpopulations may differentially express cell surface receptors, we next analysed the expression of PDGFRα, a receptor for entry into fibroblast and glioma cells." (PMID 31974453, 2020). "Everolimus has been described to improve the efficacy of dasatinib in PDGFRα-driven glioma." (PMID 32927828, 2020). "In the future, we will continue investigating how CEBPD regulates PDGFRA expression in glioma." (PMID 31300060, 2019). "Using model systems to compare two different glioma-derived RTK mutations in a more uniform setting revealed a higher amplitude of pathway activation and a feed-forward upregulation of other RTKs in NTRK-driven HGGs compared with PDGFRA-driven HGGs." (PMID 31420543, 2019). "Loss of the CTCF binding was shown to activate the enhancer of PDGFRA, a prominent glioma oncogene." (PMID 30644073, 2019). "This framework could be further refined through the incorporation of alterations in platelet-derived growth factor receptor alpha or other alterations that might be useful to consider in the diagnosis of glioma." (PMID 30592195, 2019).
glioma (continued). "In addition, the interplay between specific aspects of glioma biology (e.g. PDGFRA overexpression) and tumor host features is revealed across four different mammalian species." (PMID 29352201, 2018). "Glioma initiation events may also include point mutations in RTK pathway genes such as EGFR and PDGFRA or in MAPK pathway genes such as neurofibromin 1 (NF1)." (PMID 29616301, 2018). "Therefore, in order to make meaningful comparisons between intrinsically heterogeneous tumors, we concentrated our cross-species glioma gene expression analysis to only those tumors with high levels of PDGFRA gene expression." (PMID 29352201, 2018). "Similarly, progress in PDGFR signaling in glioma would greatly benefit from an in vivo model that is based on clinically relevant parameters such as overexpression of PDGFRα and its chronic stimulation by PDGF-A ligand." (PMID 30456354, 2018). "In addition, the results of cox regression analysis revealed PDGFRA and above oncologic factors are independent prognostic factors in gliomas." (PMID 30373180, 2018). "In isocitrate dehydrogenase (IDH) mutant gliomas, 3C revealed that a gain-of-function mutation caused hypermethylation at the CTCF binding site defining an insulated neighborhood containing the oncogene, platelet-derived growth factor receptor alpha (PDGFRA)." (PMID 30268153, 2018). "Furthermore, of all included factors, senior glioma patient, PLP2 overexpression, loss of ATRX, and positive expression of AxL, NUR77 or PDGFRA were the independent prognostic factors under cox regression analysis." (PMID 30373180, 2018). "Depletion of endogenous dynamin 2 by short hairpin RNAs (shRNAs) inhibited PDGFRα-stimulated phosphorylation and activation of Akt, extracellular signal-regulated kinase 1/2, Rac1 and Cdc42, prevented glioma cell migration and tumor growth as well as invasion in the brains of mice." (PMID 28402939, 2017). "Furthermore, we demonstrated that PDGFA/ PDGFRα upregulates GOLM1, and that GOLM1 acts as a key component in PDGFA/ PDGFRα-mediated glioma progression." (PMID 29282077, 2017). "Furthermore, the mean PDGFRA methylation was unexpectedly decreased in IDH-mutant glioma, but the mRNA levels had a modest, yet statistically insignificant, increase, similar to that noted previously." (PMID 27852048, 2017). "TCGA and Rembrandt databases and an independent cohort of primary glioma samples were analyzed for expression levels of GOLM1 based on molecular subtype (classical, mesenchymal, proneural, and neural) to reveal an association with PDGFRα." (PMID 29282077, 2017). "Future studies will determine whether glioma cells under treatment with PDGFRα specific TKI exhibit a similar adaptive regulation of PDGFRα DM copies." (PMID 25683249, 2015). "We therefore set out to then examine if PDGFRA activation, due to amplification of the PDGFRA gene, an alteration frequently found in pediatric brain tumors (eg. gliomas and medulloblastomas), affects regorafenib activity alone or in combination with DNA damaging agents." (PMID 26599335, 2015). "In our PDGFRα-driven glioma model, the copy numbers of PDGFRα vary among individual tumor cells." (PMID 25683249, 2015). "Our results suggest that nilotinib may be effective for management of a PDGFRα-dependent group of pediatric gliomas." (PMID 25732621, 2015). "Recognizing that understanding of this disease and advancement of therapy has historically been hindered by reliance upon studies of adult gliomas, we have carried out investigations of PDGFRα signaling and inhibition in cell lines derived from pediatric glioblastoma tumors." (PMID 25732621, 2015).
glioma (continued). "Taken together, these data demonstrate that Pdgfra amplification is a frequent event that can occur during early stages of malignant glioma development and may serve as an important mechanism for the upregulation of PDGFRα expression in gliomas." (PMID 25683249, 2015). "Finally, down-regulation of surface PDGFRA expression by U0126 is concordant with reduced glioma cell proliferation." (PMID 24489888, 2014). "Aberrant PDGFRA signaling plays a central role in the pathogenesis of a high proportion of gliomas." (PMID 24489888, 2014). "This miRNA involved in proliferation, self-renewal and tumor growth can modulate differentiation by targeting EGFR and PDGFRα and may be a candidate glioma tumor suppressor." (PMID 24709958, 2014). "Furthermore, the high cell proliferation rates in glioma cells with high surface PDGFRA expression was confirmed using a BrdU incorporating approach." (PMID 24489888, 2014). "However, the regulation of spatial distribution of PDGFRA in glioma cells remains poorly characterized." (PMID 24489888, 2014). "Signaling of PDGFRA or other RTKs results in activation of Ras-Raf-MEK-ERK pathway in gliomas." (PMID 24489888, 2014). "Previous reports have indicated the role of PDGFRA signaling in the activation of Ras-Raf-MEK-ERK pathway, and aberrant activation of Ras-Raf-MEK-ERK pathway can be causal for gliomas." (PMID 24489888, 2014). "In the case of gliomas, PDGFRα overexpression is related to tumor malignancy." (PMID 24709958, 2014). "Furthermore, the staining of cultured single glioma cells also showed a high rate of co-localization of PDGFRA to Rab11 and to EEA-1." (PMID 24489888, 2014). "Under our conditions, U0126 treatment caused an initial decline in ERK phosphorylation, followed by an unexpected increase in ERK phosphorylation between 3 and 18 hrs of U0126 treatment in the glioma cell lines #1, #2 and #3 with high surface PDGFRA expression." (PMID 24489888, 2014). "Interestingly, the glioma cells with high surface expression of PDGFRA showed higher proliferation rates compared with those with lower surface expression of PDGFRA." (PMID 24489888, 2014). "Using a panel of small molecule inhibitors, we tested whether the activity of Ras-Raf-MEK-ERK cascade and PI3K-AKT pathway could regulate surface PDGFRA expression in the glioma cell lines #1, #2 and #3 with high surface PDGFRA expression." (PMID 24489888, 2014). "Importantly, the regional expression pattern of Pax3 is mirrored in human glioma, revealing a subset of BSG with high PAX3 expression that associates with alterations in PDGFRA and cell cycle regulatory genes and is exclusive of ACVR1 mutations." (PMID 25330836, 2014). "Using both approaches, three groups of glioma cells could be clearly distinguished with high, intermediate or low PDGFRA expression on the surface." (PMID 24489888, 2014). "Alternatively, gliomas overexpressing PDGFRA may represent a separate molecular entity that is independent of morphological diagnosis." (PMID 23630597, 2013). "Instead, our findings in cell culture studies and expression analysis in glioma samples supported the hypothesis that PDGFRA expression was dependent on the niche factors in gliomas." (PMID 23630597, 2013). "However, the clinical relevance of PDGFRA expression in glioma subtypes and the mechanisms of PDGFRA expression in gliomas have been controversial." (PMID 23630597, 2013). "Although it is beyond the scope of this report, we speculate that additional features governing differentiation and proliferation of oligodendrocyte lineage can be detected in gliomas with enriched PDGFRA expression." (PMID 23630597, 2013). "Both the PDGFRA-high and PDGFRA-low groups contained gliomas of all morphological subtypes." (PMID 23630597, 2013). "We speculate that FGF2 mediated signaling can potentially be manipulated to suppress PDGFRA expression and thereby inhibit niche factor-dependent glioma growth." (PMID 23630597, 2013).